EGFR (epidermal growth factor receptor)
Diseases named in the same sentence as EGFR in open-access papers (continued):
Sharing a sentence is not in itself a finding about the gene and the disease.
non-small cell lung carcinoma (continued). "Recently, the results of a randomized, double-blind phase III study of erlotinib with ramucirumab (anti-VEGF therapy) or placebo in previously untreated EGFR-mutant metastatic non-small-cell lung cancer (RELAY) were reported, and the doublet therapy showed clinical benefit and results were positive." (PMID 32337094, 2020). "More recently, one of the most often targeted cell-surface entities has been EGFR (epidermal growth factor receptor, overexpressed in a variety of solid tumors such as non-small cell lung cancer, head and neck carcinoma, ovarian, kidney, and pancreatic cancer)." (PMID 32082960, 2020). "In addition, neratinib shows anticancer effects in non-small cell lung cancer, colorectal cancer, and glioblastoma through the EGFR/HER-2 pathway." (PMID 32901093, 2020). "Despite showing promising results in preclinical models, the combination of TKIs with chemotherapy (platinum-based) in EGFR-mutated non-small cell lung cancer, does not seem to be beneficial in terms of PFS and OS." (PMID 33198314, 2020). "This drug is frequently used to treat non-small cell lung cancer but could be used to treat different EGFR-mutant cancers." (PMID 32645997, 2020). "On 24 October 2016, the FDA expanded its approval as the first-line treatment for metastatic non-small-cell lung cancer with high PDL-1 expression (≥ 50%) but no EGFR or ALK mutation (Category 1 and preferred; category 2B if PDL-1 1–49%)." (PMID 32245016, 2020). "Currently, the FDA-approved qPCR test to identify Epidermal Growth Factor Receptor (EGFR) mutations, is a diagnostic test that replaces the tissue biopsy in patients with metastatic non-small cell lung cancer who would be eligible for treatment with EGFR-targeted therapy (erlotinib)." (PMID 33381456, 2020). "Moreover, combination treatment with the epidermal growth factor receptor (EGFR) inhibitor, erlotinib and miR-34 mimic and let-7 showed synergistic effects in inhibiting the growth of non-small cell lung cancer cell lines in vitro." (PMID 32486505, 2020). "Moreover, enediyne-activated, EGFR-targeted human β-defensin 1 shows therapeutic efficacy against non-small cell lung carcinoma." (PMID 33170151, 2020). "In preclinical models, chronic stress is sufficient to promote tumor growth and angiogenesis in ovarian carcinoma, breast cancer lung colonization, EGFR inhibitor resistance in non-small cell lung cancer (NSCLC), and therapy-induced anticancer immunosurveillance." (PMID 33117814, 2020). "In addition, it promotes the autophagic degradation of EGFR in non-small cell lung cancer (NSCLC), inhibits growth and angiogenesis in prostate tumors by suppressing the protein kinase B (Akt)/mammalian target of rapamycin (mTOR)/P70S6K pathway." (PMID 32116702, 2020). "Moreover, it has been demonstrated that EGFR inhibitor resistance in NSCLC (Non-Small-Cell Lung Carcinoma) correlates with the activation of the β2-AR pathway through an IL-6 dependent mechanism." (PMID 33051434, 2020). "Of note, the activation of MET by HGF has been suggested as a potential mechanism of acquired tyrosine kinase inhibitor (TKI) resistance to gefitinib in epidermal growth factor receptor (EGFR)-mutant non-small cell lung cancer (NSCLC) and to vemurafenib itself in BRAF-mutant melanoma." (PMID 33553157, 2020). "A high percentage (40–89%) of non-small cell lung carcinomas shows overexpression of EGFR." (PMID 33353059, 2020). "EMT has been identified as a major contributor of acquired resistance against EGFR-TKIs in non-small-cell lung cancers, while protein-level pan-cancer studies have highlighted an EMT-status-dependent efficacy of several EGFR inhibitors and other targeted therapies." (PMID 32517019, 2020). "Well-known examples of mutated oncogenic members are found in the epidermal growth factor receptor/Erb-B2 receptor tyrosine kinases (EGFR/ERBB) family involved in lung adenocarcinoma and other non-small cell lung carcinomas, breast cancer, and colorectal and gastric cancer." (PMID 30987166, 2019).
non-small cell lung carcinoma (continued). "Clinical data acquired over the last decade on non-small cell lung cancer (NSCLC) treatment with small molecular weight Epidermal Growth Factor Receptor (EGFR) inhibitors have shown significant influence of EGFR point mutations and in-frame deletions on clinical efficacy." (PMID 30626888, 2019). "The role of brain surgery (BS) on the survival of patients with non-small-cell lung cancer (NSCLC) and brain metastases (BM), particularly those with epidermal growth factor receptor (EGFR) mutations under tyrosine kinase inhibitors (TKIs) is yet to be defined." (PMID 31728013, 2019). "In non-small cell lung cancer (NSCLC), the expression of an EMT gene signature, which included AXL expression, was associated with resistance to treatment with epidermal growth factor receptor (EGFR) and phosphatidylinositol 3-kinase (PI3K) inhibitors." (PMID 31681587, 2019). "Nowadays, molecular testing in advanced non-small cell lung cancer (NSCLC) patients includes screening for targetable alterations, e.g., EGFR mutations or ALK rearrangements, and, in addition, factors predictive of response to immunotherapy, thus, immune checkpoint inhibitors (ICIs)." (PMID 31374957, 2019). "EGFR inhibitors such gefitinib, erlotinib, and lapatinib are now routine treatments in non-small cell lung cancer and breast cancer and could be considered for off-label use in craniopharygiomas." (PMID 31712784, 2019). "A previous study reported that non-small cell lung cancer with ANT overexpression may exhibit resistance to epidermal growth factor receptor/tyrosine kinase therapy." (PMID 31906234, 2019). "For example, some studies evaluated the cost effectiveness of erlotinib for all non-small cell lung cancer patients rather than just those with EGFR mutations." (PMID 31087278, 2019). "MET amplification is associated with acquired resistance to first-generation epidermal growth factor receptor (EGFR)-tyrosine kinase inhibitors (TKIs) in treating non-small-cell lung cancer (NSCLC); however, the therapeutic strategy in these patients is undefined." (PMID 30791921, 2019). "Several studies have connected sensitivity to EGFR-TKIs and survivin in non-small cell lung cancer." (PMID 30729097, 2019). "Similarly, PD-L1 expression was shown to positively correlate with EGFR expression in non-small-cell lung carcinoma cell lines that were treated in vitro with EGF." (PMID 30770752, 2019). "Completely resected stage II~IIIA lung adenocarcinoma with EGFR-tyrosine kinase (TKI) sensitizing mutation (mEGFR) is treated with cisplatin-based adjuvant chemotherapy, which is similar to other non-small cell lung cancers irrespective to the EGFR mutation status." (PMID 31632498, 2019). "Additionally, MST1R (RON) sustains MET oncogene addiction, while EGFR dependence in non-small cell lung cancer (NSCLC) involves MST1R (RON)." (PMID 30863365, 2019). "On the other hand, gefitinib is a specific inhibitor of the epidermal growth factor receptor (EGFR) tyrosine kinase and has been shown to suppress the activation of EGFR signaling required for cell survival and proliferation in non-small-cell lung-cancer (NSCLC) cell lines." (PMID 30845677, 2019). "The significance of EGFR mutations remains unclear since there is evidence that, in non-small-cell lung cancer (NSCLC), mutations in the TK domain of EGFR are predictive for the response to gefitinib." (PMID 31546690, 2019). "Furthermore, we have detected such tumorospheres in non-small-cell lung cancer (NSCLC) patients progressing under EGFR-directed tyrosine kinase inhibitor therapy which had undergone NSCLC-SCLC transformation." (PMID 35582592, 2019). "The FLAURA trial established osimertinib, a third-generation epidermal growth factor receptor (EGFR) tyrosine kinase inhibitor (TKI), as a viable first-line therapy in non-small cell lung cancer (NSCLC) with sensitizing EGFR mutations, namely exon 19 deletion and L858R." (PMID 30875928, 2019).
non-small cell lung carcinoma (continued). "To date, there are no biomarkers used in clinical practice that can predict tumor response to cetuximab in HNSCC patients despite predictive biomarkers for response to EGFR inhibitors being well established in non-small cell lung cancer (NSCLC) and colorectal cancer (CRC)." (PMID 30890189, 2019). "Non-small cell lung carcinoma (NSCLC), the leading cause of cancer mortality worldwide, has known driver mutations of nodes on this pathway in ~75% of cases, including: ~30% KRAS, ~11% EGFR, ~7% BRAF and ~11% NF1 mutations." (PMID 31182717, 2019). "EGFR is an important drug target for the treatment of non-small cell lung carcinoma (NSCLC)." (PMID 31862911, 2019). "As a matter of fact, only a few types of cancer have been successfully treated with a single drug, e.g., imatinib in chronic myeloid leukemia, gefitinib (EGFR inhibitor) in mutant EGFR non-small cell lung cancer, and PLX4032 (BRAF inhibitor) in mutant BRAF melanoma." (PMID 30909600, 2019). "Besides our research, another group has proved that active EGFR phosphorylated Beclin-1 to inhibit autophagy in non-small cell lung carcinoma (NSCLC) cells." (PMID 31378785, 2019). "Recent studies have shown that a small fraction of cancer cells that survive initial treatment (e.g., anti-epidermal growth factor receptor (EGFR) erlotinib in non-small cell lung cancer) eventually regain their sensitivity to the same drug after a “drug holiday”7,8." (PMID 31844050, 2019). "Indeed, BCR-ABL-positive CML and EGFR mutation-positive non-small cell lung cancer (NSCLC) cells expressing BIM-γ exhibit resistance to imatinib and gefitinib (EGFR TKI), respectively." (PMID 30463359, 2018). "Within non-small cell lung cancer (NSCLC) cells it was found that with the suppression of E-Cadherin, ZEB1 has the ability to increase invasion via transcriptional activation of MMP-2 as well as cause aberrant EGFR signaling." (PMID 32309604, 2018). "Clinical trials are currently being done to study Metformin in combinatory treatments with an assortment of molecularly targeted therapies, including EGFR inhibitors, as well as its effect on overall survival and treatment-related toxicity in advanced stage non-small cell lung cancer patients." (PMID 29973561, 2018). "Consequently, overactivation of EGFR signaling pathways is detected in various malignant tumors, including non-small cell lung cancer (NSCLC), breast cancer, head and neck cancer, colon cancer, ovarian cancer, and the like." (PMID 29455669, 2018). "In contrast to non-small cell lung cancer, the relatively low number of MPM cases combined with the low prevalence of drug-targetable EGFR mutations in MPM compromises the investigation and use of selective EGFR inhibitors in the treatment of mesothelioma." (PMID 29848954, 2018). "Gefitinib is the FDA approved drugs for EGFR mutant non-small cell lung cancer patients." (PMID 29126216, 2018). "As a third-generation epidermal growth factor receptor (EGFR) tyrosine kinase inhibitor (TKI), osimeritnib is the standard treatment for patients with non-small cell lung cancer harboring the EGFR T790M mutation; however, acquired resistance inevitably develops." (PMID 29386539, 2018). "Epidermal growth factor receptor (EGFR) is expressed by more than 50% of non-small cell lung carcinoma cells and thus may a good candidate." (PMID 30108584, 2018). "Overexpression of EGFR is associated with resistance to chemotherapy and radiotherapy and poor prognosis in many cancers, such as head and neck squamous cell carcinoma (HNSCC), breast cancer, and non-small-cell lung cancer (NSCLC)." (PMID 30231504, 2018). "EGF receptor (EGFR) can be detected as overexpressed in some tumors, such as prostate cancer, bladder cancer, breast cancer, ovarian cancer, non-small cell lung cancer, and head and neck cancer, and has also been found to play an important role in the progression of several human malignancies." (PMID 29470420, 2018).
non-small cell lung carcinoma (continued). "Approximately 25 to 40% of all non-small-cell lung cancer (NSCLC) patients will develop brain metastases (BMs) during their disease course, and the risk is even higher in patients with epidermal growth factor receptor (EGFR) mutation." (PMID 30619745, 2018). "Gefitinib, an epidermal growth factor receptor (EGFR) tyrosine kinase inhibitor (EGFR-TKI), is used clinically as first-line therapy in patients with advanced non-small cell lung cancer (NSCLC) with EGFR activating mutations, but the inevitable development of acquired resistance limits its efficacy." (PMID 30515095, 2018). "They found that some traditional CT features, including air bronchogram, pleural retraction, small lesion size and absence of fibrosis, were associated with EGFR mutations in non-small cell lung cancer." (PMID 30547844, 2018). "Clinically, EGFR is overexpressed in 40 to 89 percent of non-small cell lung cancers." (PMID 29856819, 2018). "Given that EGF activates AMPK to drive Skp2-mediated ubiquitination and activation of Akt, we next examined whether the AMPK-Skp2-Akt axis contributes to the resistance to EGFR targeting therapy in non-small cell lung cancer cells (NSCLC)." (PMID 30413706, 2018). "Non-small cell lung cancer-derived EVs containing amphiregulin, a ligand of epidermal growth factor receptor (EGFR), activate the EGFR pathway in pre-osteoclasts, which in turn promotes the expression level of receptor activator of nuclear factor kappa-B ligand (RANKL)." (PMID 29534557, 2018). "Thus the assessment of molecular receptors such as human epidermal growth factor receptor 2 (HER2) in breast cancer and epidermal growth factor receptor (EGFR) in non-small cell lung cancer is now routine to guide treatment regimens." (PMID 29439481, 2018). "In recent years, epidermal growth factor receptor tyrosine kinase inhibitors have been recommended by many guidelines as first-line drugs for advanced non-small cell lung cancer (NSCLC) with EGFR gene mutations and no resistance." (PMID 30172273, 2018). "However, few studies have prospectively investigated the clinical relevance between the presence of EGFR or KRAS mutations and occurrence of venous thromboembolism(VTE) in patients with non-small cell lung cancer (NSCLC)." (PMID 29743116, 2018). "Apart from SCC, this peptide ligand of EGFr has potential applications in targeting treatments of patients with EGFr-positive malignancies, which include non-small cell lung cancer, esophageal, gastric, prostate, colorectal, bladder, pancreatic, ovarian and renal cancers." (PMID 29855618, 2018). "For metastatic non-small cell lung cancer with no epidermal growth factor receptor mutations or anaplastic lymphoma kinase gene rearrangements, programmed cell death-1 (PD-1) blockade is preferentially recommended post first-line chemotherapy." (PMID 30544423, 2018). "The epidermal growth factor receptor (EGFR) is known to be highly expressed in non-small cell lung cancer, and studies have been conducted investigating nano-formulations with EGFR targeting ligands for the delivery of cisplatin to the cancer tissue following inhalation." (PMID 30021074, 2018). "Approximately 33% of patients with non-small cell lung cancer (NSCLC) tumors and epidermal growth factor receptor mutations develop BMs, which are targetable with different generations of tyrosine kinase inhibitors (TKIs: gefitinib, erlotinib, afatinib, icotinib, and osimertinib)." (PMID 29881714, 2018). "In addition, CXCL8 can stimulate cell proliferation in non-small cell lung cancer through EGFR transactivation." (PMID 30034618, 2018). "A cohort of 227 NSCLC (non-small cell lung cancer) adenocarcinoma patients was treated with erlotinib irrespective of EGFR-mutational status." (PMID 29448920, 2018). "EGFR is frequently overexpressed in many cancers including non-small cell lung cancer (NSCLC)." (PMID 30011810, 2018).
non-small cell lung carcinoma (continued). "Moreover, phospho-Akt levels are increased in most clinical specimens obtained from EGFR-mutant non-small-cell lung cancer patients with acquired EGFR tyrosine kinase inhibitor resistance." (PMID 28871105, 2017). "JO22903 (JapicCTI-101085) was a single-arm, multicenter, phase II, open-label, non-randomized study of first-line erlotinib monotherapy in EGFR mutation-positive non-small-cell lung cancer." (PMID 27659294, 2017). "The humoral IgG immune response against EGFR was investigated in patients with non-small cell lung cancer receiving gefitinib and it was suggested that determining anti-EGFR IgG antibody levels may have prognostic significance." (PMID 29354119, 2017). "Notably, liquid biopsy already represents a reality in clinical practice, as demonstrated by the EGFR genetic testing for non-small cell lung cancer." (PMID 29246026, 2017). "One of the most commonly used liquid biopsy analysis is the search of epidermal growth factor receptor (EGFR) mutations, which predicts responsiveness to EGF receptor (EGFR)-tyrosine kinase inhibitors in a distinct clinicopathologic subset of non-small-cell lung cancer patients." (PMID 29246026, 2017). "Prediction of treatment outcome of non-small cell lung cancer (NSCLC) with EGFR inhibitors on the basis of the genetic analysis of the tumor can be incorrect in case of rare or complex mutations, bypass molecular activation pathways, or pharmacodynamic variations." (PMID 28671975, 2017). "In addition, the anti-oncogene function of miR-218 has been reported in several types of cancers through targeting several oncogenes, such as Rictor (oral cancer), EGFR (non-small cell lung cancer), ROBO1 receptor (gastric cancer) and LAMB3 (cervical cancer)." (PMID 29152130, 2017). "For instance, the identification of KRAS mutation at codons 12 and 13 in metastatic CRC predicts the lack of benefit from EGFR-targeted antibodies, and for the non-small cell lung cancer patients with EGFR del746_A750 or L858R, they are very responsive to EGFR tyrosine kinase inhibitors." (PMID 28769798, 2017). "The recommendations regarding the optimum treatment for advanced non-small-cell lung cancer (NSCLC) patients with wild-type (WT) epidermal growth factor receptor (EGFR) tumors remain unclear." (PMID 29029530, 2017). "We also analysed recently published data of the site of recurrence of 481 resected non-small cell lung cancers according to KRAS and EGFR mutation status, and found that KRAS mutations overall were highly significantly (P<0.0001; Fischer's exact test) associated with pleural recurrence." (PMID 28508873, 2017). "Activation of the pathway has been associated with clinical resistance to TKIs such as imatinib for gastrointestinal stromal tumors (GIST), epidermal growth factor receptor (EGFR) TKIs in non-small cell lung cancer and to lapatinib in pre-clinical breast cancer models." (PMID 28464908, 2017). "These therapies have improved patient responses in many tumor types that previously had few effective treatments, such as RAF inhibitors for metastatic melanoma and epidermal growth factor receptor (EGFR) inhibitors for EGFR mutant non-small cell lung cancer (NSCLC)." (PMID 28431544, 2017). "Non-small cell lung cancer (NSCLC) accounts for about 85% of cases and includes adenocarcinomas, characterized by RAS or EGFR mutations, squamous cell carcinoma with FGFR1 amplification, PTEN or PIK3CA mutations, and large cell carcinoma, which are highly heterogeneous." (PMID 28672805, 2017). "Moreover, HDACi have been demonstrated to sensitize malignant cells to EGFR inhibition in non-small cell lung carcinoma." (PMID 28674496, 2017).